HMGB1 (high mobility group box 1)
Diseases named in the same sentence as HMGB1 in open-access papers (continued):
Sharing a sentence is not in itself a finding about the gene and the disease.
cancer (continued). "Cancer cells with compound-induced ferroptosis were found to release HMGB1 in an autophagy-dependent manner." (PMID 36158661, 2022). "In a mouse model of lung metastatic cancer, C5a was shown to induce the expression of high mobility group box 1 (HMGB1) receptors TLR4 and rage in PMN-MDSCs, while the formation of NETs was in turn dependent on HMGB1 produced by cancer cells." (PMID 36237333, 2022). "The second mechanism is through regulating the release of HMGB1 from cancer cells, thus mediating the anticancer immune response." (PMID 35359956, 2022). "It has been shown that ferroptosis of cancer cells release high-mobility group box 1 (HMGB1) in an autophagy dependent manner, which increases the immunogenicity of cancer cells and promotes the maturation of DC cells." (PMID 35351131, 2022). "More significantly, HMGB1 has been described as a damage-associated molecular pattern (DAMP) molecule in a number of infectious diseases and cancer." (PMID 35280439, 2022). "Assuming that the concentration of HMGB-1 is proportional to the density of cancer cells, this activation rate is proportional to a linear combination of NKN+N and MKM+M, where KN and KM are constants." (PMID 35015785, 2022). "HMGB1-RAGE ligation has been found to activate several signaling pathways in different cancer types." (PMID 35610613, 2022). "Cluster 1, as with cancer and necrotic cells, achieves the highest steady state concentration in HMGB1." (PMID 36294824, 2022). "Cytoplasmic HMGB1 boosts autophagy as well as suppresses apoptosis of cancer cells in anticancer immunotherapy." (PMID 36230798, 2022). "It is of extreme interest to explore the prognostic and biomarker potential of HMGB1 in cancer since HMGB1 expression is frequently enhanced in advanced cancer stages and correlates with poorer prognosis in most human cancers (and refs. therein)." (PMID 35454134, 2022). "A high extracellular HMGB1 concentration was previously shown to be closely associated with metastasis by promoting the mobility and invasiveness of cancer cells through the activation of the HMGB1-RAGE signaling pathway." (PMID 35328684, 2022). "HMGB1, a Damage-Associated Molecular Patterns (DAMP) associated with alarm signaling of innate defense, is actively secreted by cancer cells during stress including hypoxia." (PMID 36248858, 2022). "Analysis of cancer genome databases revealed an inverse relationship between HMGB1 mRNA levels and overall survival of GB patients." (PMID 35193644, 2022). "Second, in spite of the large number of characterized histone regulators, only little is known about potential alterations in histone regulators that have an actual impact on steady state histone levels in cancer, as in the case of HMGB1." (PMID 36030322, 2022). "In some cancers, HMGB1 inhibits apoptosis by triggering autophagy and is considered an important regulator of autophagy." (PMID 34966671, 2021). "In order to further prove the effect of HMGB1 in cancer cachexia, we used lentivirus to knock down the expression of HMGB1 in CT26 cells for cell and animal experiment." (PMID 34867338, 2021). "All of these peculiarities make HMGB1 a critical molecular target in a variety of human diseases, such as cancer." (PMID 34805222, 2021). "DAMPs can be divided into three classes, exposed on the cell surface including calreticulin (CRT), released by cancer cells passively (such as HMGB1 and mitochondrial DAMPs), secreted by cancer cells actively (such as ATP)." (PMID 34094967, 2021). "Cancer cells induced by pz I-PDT or pz III-PDT released HMGB1 and ATP and were engulfed by bone marrow-derived dendritic cells, which then matured and became activated in vitro." (PMID 33785775, 2021).
cancer (continued). "The activity of the HMGB1/RAGE/NF-κB pathway in the cancer cells and TAMs was then probed for the mechanism of PD-L1 induction and PD-1 induction." (PMID 34488792, 2021). "ICD is characterized by an alteration in the levels of calreticulin (CRT) in the plasma membrane of cancer cells and the release of damage-associated molecular pattern (DAMP) molecules, such as ATP and high mobility group B1 (HMGB1), from dying cancer cells." (PMID 33919653, 2021). "A recent study demonstrated that triptolide significantly inhibited the viability and clonogenic ability of cancer cells by downregulating HMGB1 expression, thereby suppressing breast cancer growth." (PMID 34599143, 2021). "The IHC score for HMGB1 in the normal and cancer cells of the cancer tissue in the CC + GL group was lower than that in the CC group." (PMID 33807620, 2021). "Ferroptotic cancer cells release HMGB1 to promote the inflammatory responses of macrophages through binding to AGER." (PMID 34796174, 2021). "HMGB1 is a highly conserved nuclear protein that has been proven to be upregulated in various kinds of cancers." (PMID 34933679, 2021). "HMGB1 expression is increased and colocalizes with lysosomal proteins in many types of cancer cells." (PMID 33140586, 2021). "HMGB1 is the DAMP most associated with cancer and has been shown to play an active role in cancer-associated inflammation and pathogenesis." (PMID 34359823, 2021). "In glioblastoma, HMGB1 derived from NETs promotes the proliferation of cancer cells by interacting with RAGE and activating the NF-κB pathway." (PMID 34758877, 2021). "The role of HMGB1 as a “danger signal” or alarmin in cancer progression has been extensively studied in the last decade." (PMID 34234778, 2021). "CRT exposed on the surface of dying cancer cells promotes the engulfment of dying cancer cells by antigen-presenting cells (APCs), whereas HSPs and HMGB1 bind to TLR4, enhancing APC activation and antigen cross-presentation." (PMID 34683961, 2021). "The inhibition of circ_0005909 has been shown to suppress cell viability, invasion, EMT and migration in vitro and to decrease cancer growth in vivo partially by regulating miR-936/HMGB1." (PMID 33617480, 2021). "In particular, it has been demonstrated that either chemotherapy or radiotherapy lead to HMGB1 release from dying cancer cells, promoting antigen processing and presentation on dendritic cells (DCs) through TLR4-MyD88 axis." (PMID 33540645, 2021). "Further research is warranted to explore the roles of exosomes and exosomal HMGB1 in platelet-driven cancer malignancy and to investigate the anticancer targets of antiplatelet drugs." (PMID 33669632, 2021). "Serving as a valuable clue as to where to begin the mechanistic exploration, another interesting observation caught our attention, which was that Nano-DOX also stimulated cancer cells to release high mobility group box 1 (HMGB1)." (PMID 34488792, 2021). "The high levels of COX-2 and HMGB1 promoted inflammation and DNA damage, marked by 8-NitroG and 8-OxodG, and the dedifferentiation of cancer cells into YAP1- and SOX9-positive CSCs in the colonic tissue." (PMID 33807620, 2021). "Here we report for the first time that the role of HMGB1 in anti-cancer immune evasion is determined by the TLR4." (PMID 34234778, 2021). "Recent studies have delineated the interaction of RAGEs with a wide range of acidic ligands, viz., AGEs, S100s, high-mobility group box1 (HMGB1), and their role in promoting cancer." (PMID 33466626, 2021). "Extracellular HMGB1 released by dying cancer cells and its receptor TLR4 on dendritic cells have been shown to be necessary for ICD." (PMID 34561422, 2021).
cancer (continued). "We discovered immunogenic surrender while testing ICD as a possible mechanism for the anti-cancer therapeutic potential of BoxA, a truncated form of HMGB1 (aa 2–89) endowed with anti-inflammatory properties." (PMID 34561422, 2021). "High Mobility Group Box 1 (HMGB1) is involved in cancer cell proliferation, autophagy, metastasis and epithelial-mesenchymal transition (EMT) via regulating various signaling pathways." (PMID 33926347, 2021). "Mounting evidence shows that HMGB1 can promote the malignant progression of different types of cancer through the NF-κB signalling pathway 15-17." (PMID 34539874, 2021). "Upon cancer cell death, HMGB1 is released in the surrounding TME where it physically interacts with several pattern recognition receptors (PRRs), such as TLR2, TLR4, and RAGE, thus stimulating the innate immune system." (PMID 33540645, 2021). "We also detected significantly higher HMGB1 expression in CT26 cancer cells than the normal colonic epithelium (NCM460 cells)." (PMID 34867338, 2021). "HMGB1 is a secretory protein, and is reported to be related to cancer initiation, progression, and invasion." (PMID 34552063, 2021). "We also tested ATP and HMGB1 release in cancer cells, two crucial signals during DC recruitment and maturation." (PMID 34887404, 2021). "To understand the potential mechanisms behind the differential expression and immunological relevance of HMGBs in different cancer types, we explored correlated genes of HMGB1/2/3 in three representative cancer types and performed GSEA for them, respectively." (PMID 34777483, 2021). "Here, we identified the expression of candidate markers including HMGB1, SOX9, and YAP1, implicated in the cancer development of patients with CCA using genomic datasets from GEO." (PMID 35201494, 2021). "Due to its pro-inflammatory effects, HMGB1 is an important drug target and a potential biomarker for various neurodegenerative diseases and cancers." (PMID 34305932, 2021). "The (HMGB)-1 is the focus of recent cancer research, because it plays a critical role in cancer development, progression and metastasis by activation of cancer cells, enhancement of tumour angiogenesis and suppression of host anti-cancer immunity." (PMID 33802531, 2021). "Although HMGB1 has been shown to have important roles in cancer, the results of various studies have been contradictory." (PMID 33558529, 2021). "In TLR4-positive cancer cells, HMGB1 triggers the formation of an autocrine loop which induces galectin-9 expression." (PMID 34234778, 2021). "Understanding the mechanism by which HMGB1 regulates the interplay between actin and microtubule cytoskeleton during cancer metastasis is a critical issue." (PMID 33807275, 2021). "The reciprocal crosstalk between platelets and cancer cells as well as the potential involvement of HMGB1 were further investigated using dipyridamole." (PMID 33669632, 2021). "The positive immunohistochemical staining of HMGB1 was dark brown, and the staining intensity and number of positive cells in cancer tissues was significantly higher than that of adjacent tissues." (PMID 33391448, 2021). "We demonstrate that upon TLR2 stimulation, EAC cancer cells upregulate HMGB1, which translocates to the cytosol before being released extracellularly." (PMID 33922955, 2021). "Using K562-differentiated megakaryocytes and murine platelets, conditioned medium and exosomes obtained from megakaryocytes and platelets contained HMGB1 and promoted cancer cell survival, as well as protected cancer cells from doxorubicin cytotoxicity." (PMID 33669632, 2021). "Recent experimental data prove that cancer cells undergoing ferroptosis release High mobility group Box 1 (HMGB1) in an autophagy-dependent manner." (PMID 33540645, 2021). "TLR2, TLR4, TLR9, and RAGE have been identified as the most common receptors for HMGB1 on cell surface in different cancer models and patients." (PMID 33614649, 2021).
cancer (continued). "Cancer cells expressing TLR4 release TGF-β in response to stimulation with HMGB1 followed by TGF-β-induced upregulation of galectin-9 expression, forming such an HMBG1-triggered autocrine loop." (PMID 34234778, 2021). "Despite that the overexpression of HMGB1 in cancers was the most prevalently reported, we found that HMGB3 was highly expressed in the largest variety of cancers and altered most frequently." (PMID 34777483, 2021). "When HMGB1 is released into the TME because of cancer cell death, it can stimulate the innate immune system by interacting with several pattern recognition receptors." (PMID 34568341, 2021). "Upregulation of HMGB1 expression has been unequivocally observed in various cancers such as HCC and lung cancer." (PMID 34778055, 2021). "By analysis of The Cancer Genome Atlas Database, we found that HMGB1 is downregulated in LUAD patients compared to healthy control, and high level of HMGB1 is significantly associated with poor survival rate." (PMID 34552063, 2021). "In the GEPIA2 database, HMGB1/2/3 were significantly differentially expressed in a total of 8, 14, and 24 types of TCGA cancers, respectively, compared with the corresponding normal controls." (PMID 34777483, 2021). "The results suggest further studies of the mechanism are warranted to determine the role of sulfonyl HMGB1/ RAGE-dependent biology in cancer because it offers an interesting experimental therapeutic strategy." (PMID 34943830, 2021). "Concerns about the intratumoral application of HMGB1 in malignant tumors are based on the observation that reactive oxygen species, which are often elevated in the TME, can oxidize HMGB1 and neutralize its immunostimulatory activity." (PMID 34025657, 2021). "Stromal cell-derived factor 1 and high-mobility group box 1 released by CAFs also contributed to cancer proliferation and stemness." (PMID 34735373, 2021). "The potency of such treatments in inducing in vivo ICD of residual cancer cells were detected via the immunofluorescence staining with anti-HMGB1 and anti-CRT primary antibodies." (PMID 34262038, 2021). "Beyond intracellular functions, HMGBs, especially HMGB1, can be actively secreted by cancer cells per s, infiltrating immune cells, and stromal cells, or passively released from necrotic cells into extracellular milieu in response to various stimuli." (PMID 34777483, 2021). "There is evidence that different types of ferritic cancer cells can release HMGB1, a damage-related molecule, in a ferroptosis-dependent manner, and can then obtain the characteristics of immune stimulation and act as an adjuvant." (PMID 34820374, 2021). "HMGB1 plays a significant role in many cancers and has promising clinical application prospects as a therapeutic target." (PMID 34257571, 2021). "HMGB proteins are functionally related to cancer progression and HMGB1 overexpression has been detected in cancerous cells of prostate epithelial origin." (PMID 34680291, 2021). "They described that carbon ion radiation increased the secretion of high mobility group box 1 (HMGB1) in human cancer cell lines." (PMID 34188135, 2021). "Many reports have demonstrated that subcellular localization and secretion of HMGB1 plays a major role as a positive regulator of autophagy in chemotherapy resistance in various cancers." (PMID 34778055, 2021). "PC cells had the highest release of HMGB1 as compared to different cancer cell lines (e.g., breast, lung and bladder)." (PMID 34805222, 2021). "Previous reports have suggested that High-Mobility Group Box 1 (HMGB1) is involved in drug resistance in several cancers." (PMID 34966671, 2021). "Given the role of KRAS in cancer, and the propensity of other oncogene promoters to contain G4 structures, this regulatory mechanism involving HMGB1 warrants further investigation." (PMID 34680084, 2021).
cancer (continued). "G-chlorin PDT induces translocation of CRT and HMGB1 from the nucleus to the cytosol and cell surface of cancer cells." (PMID 33670714, 2021). "Knockdown of endogenous HMGB1 with short hairpin RNA (shRNA) can inhibit the proliferation of cancer cells by reducing Bcl-2 and activating Bax." (PMID 34867338, 2021). "Recent findings in chronic inflammatory disorders and cancer suggest that HMGB1 enhances immunosuppressive properties of T cells either directly or indirectly." (PMID 34209240, 2021). "The interaction of RAGE with its ligand HMGB1 induces epithelial-mesenchymal transition (EMT) of cancer cells." (PMID 34572138, 2021). "The release of nuclear HMGB1 in cancer cells treated with SeNps was also confirmed using immunofluorescence microscopy." (PMID 34771499, 2021). "Integrating the results of two steps of survival analyses, high expression of HMGBs suggested unfavorable prognosis in the following cancers: HMGB1 in ACC; HMGB2 in ACC, KIRP, LGG, LIHC, MESO; and HMGB3 in BRCA, ESCA, SARC, and SKCM." (PMID 34777483, 2021). "The structure of NETs formed by granule proteins and DNA induces the proliferation of cancer cells through high mobility group protein B1 (HMGB1) and NE." (PMID 34674757, 2021). "The exposure of CRT and the release of ATP and HMGB1 were observed in cancer cells treated with the helical polypeptides." (PMID 33854870, 2021). "HMGB1 released by ferroptotic cancer cells is a prototypical DAMP involved in the immunogenicity of cancer cells, and it triggers an inflammatory response in macrophages through binding to advanced glycosylation end-product-specific receptor (AGER/RAGE)." (PMID 34796174, 2021). "More recently, HMGB1 was discovered to be a crucial cytokine that mediates pathological effects in sepsis, arthritis, cancer, and other diseases." (PMID 34916485, 2021). "Our study revealed that CML-HMGB1 correlates with oxidized HMGB1 and promotes cancer malignancy more than oxidized HMGB1, but its structural differences and receptor affinity have not been clarified." (PMID 34068442, 2021). "It has been found that HMGB1 knockout mice die shortly after birth, and the increased HMGB1 expression inhibits apoptosis in various types of cancer cells." (PMID 33603790, 2021). "Several studies have reported the overexpression and release of HMGB1 in breast, gastric, hepatocellular, colorectal, and pancreatic cancers and NSCLC." (PMID 34966671, 2021). "Other studies have demonstrated that cancer cells that have undergone ferroptosis can release high mobility group Box 1 (HMGB1) in an autophagy-dependent manner." (PMID 34568341, 2021). "The binding of ABOX as an antagonist of HMGB1 to the receptor of HMGB1 named receptor for advanced glycation end products (RAGE) leads to inhibition of HMGB1 properties in cancer progression, especially in angiogenesis." (PMID 34249257, 2021). "Crucially, we detected some of the main biomarkers of ICD, namely, the translocation of calreticulin/ERp57, the release of HMGB1 and ATP, and the secretion of pro-inflammatory cytokines from the SeNps-treated dying cancer cells." (PMID 34771499, 2021). "In particular, HMGB1 plays paradoxical roles in promoting cancer cell proliferation and inhibiting malignant cell survival." (PMID 34988076, 2021). "The high-mobility group box 1 protein (HMGB1) is a secreted cytokine immunomodulator with central roles in autoimmune, infectious, and inflammatory pathologies especially related to cancer and cardiovascular disease." (PMID 34970357, 2021). "In cancer, HMGB1 plays dual roles in both pro- or anti-carcinogenesis by regulating multiple cellular processes such as proliferation, angiogenesis, and invasion." (PMID 34552063, 2021).